CASP8 (caspase 8)
Diseases named in the same sentence as CASP8 in open-access papers (continued):
Sharing a sentence is not in itself a finding about the gene and the disease.
inflammatory skin disease (5 papers, 2014 to 2025). Inflammatory skin disorders covers a broad category that includes many conditions ranging in severity, from mild itching to grave medical health complications These disorders are common in people of all ages and races. "This is consistent with previous reports that Caspase-8 loss leads to severe inflammatory skin disease and chronic inflammation of the liver and intestine." (PMID 39625985, 2024). "FADD or caspase-8 deficiency in skin results in spontaneous necrosis of keratinocytes in vivo, causing an inflammatory skin disease." (PMID 33238518, 2020). "Casp8 deficiency results in early embryonic lethality in mice, and loss of Casp8 or Fadd in the skin leads to keratinocyte hyperplasia and inflammatory skin disease." (PMID 25443632, 2014). "While engagement of TNF-related apoptosis-inducing ligand (TRAIL) receptors and subsequent caspase-8–dependent apoptosis represent a plausible mechanism based on analogies to other inflammatory skin diseases, direct evidence for TRAIL-R1/R2 involvement in chronic sclerotic GvHD remains limited." (PMID 41479908, 2025). "The key molecules in cell death signaling, caspase-8, FADD, and cFLIP, were shown to be essential for the maintenance of skin homeostasis, since loss of any of these molecules resulted in severe inflammatory skin disease." (PMID 33238518, 2020).
lymph node metastasis (5 papers, 2015 to 2023). "Correlation and regression analysis indicated that CASP8 expression was considerably associated with differentiation (p = 0.004) and lymph node metastasis (p = 0.044)." (PMID 36533709, 2023). "Higher levels of cCASP8 were associated with better DSS among the patients with lymph node metastases, suggesting that inactivating mutations in CASP8 might be linked to a poorer clinical outcome." (PMID 37443405, 2023). "However, in later stage HNCs with lymph node metastasis, high caspase-8 and DR5 together was significantly associated with poor disease-free and overall survival." (PMID 33810241, 2021). "CASP8 expression was significantly correlated with the degree of differentiation (P = 0.004) and lymph node metastasis (P = 0.044)." (PMID 36533709, 2023). "This is also true for HNCs with lymph node metastasis that possess high FADD expression alone or in combination with high DR5 or caspase-8 expression." (PMID 33810241, 2021).
lymphopenia (5 papers, 2020 to 2025). Reduction in the number of lymphocytes. "Enhanced numbers of Ripk1ΔCD4 naive T cells expressed the proliferation marker Ki-67+ despite the peripheral lymphopenia and single-cell RNA sequencing revealed T cell-specific transcriptomic alterations that were reverted by additional caspase-8 deficiency." (PMID 38734851, 2024). "In order to identify the mechanism of cell death implicated in the T cell lymphopenia, we showed that additional caspase-8 deletion in Ripk1ΔCD4Casp8 ΔCD4 mice resulted in a complete restoration of the T cell numbers with similar single-cell transcriptomic profiles as wild-type littermates." (PMID 38734851, 2024). "Collectively, caspase-8 cleavage together with RIPK3 or MLKL suppresses the intrinsic lymphopenia of hematopoietic stem cells." (PMID 35064213, 2022). "In line with this, we observed elevated expression of pro‐apoptotic molecules (e.g. CASP3, FAS, CASP8, IRF1 etc.)in coinfected patients with severe disease, suggesting that cell apoptosis may be associated with the lymphopenia observed in severe coinfection." (PMID 41163794, 2025). "Altogether, these data demonstrate that peripheral T cell lymphopenia due to the absence of RIPK1 scaffold function is caused by caspase-8-mediated apoptosis." (PMID 38734851, 2024). "In light of the cellular rescue by additional caspase-8 deletion, the reported senescent T cell phenotype following RIPK1 deficiency may be caused by the lymphopenia-induced dysbalance leading to age-related sequelae." (PMID 38734851, 2024). "In summary, caspase-8 auto-cleavage plays an important role in regulating cell death and immune cell homeostasis, that is, mediating apoptosis, suppressing necroptosis, and protecting from lymphopenia." (PMID 35064213, 2022). "Furthermore, Ripk1ΔCD4Casp8 ΔCD4 and Ripk1ΔCD4Tnfr1−/− double-knockout mice rescued the peripheral T cell lymphopenia, revealing that RIPK1-deficient naive CD4+ and CD8+ cells and FoxP3+ regulatory T cells specifically die from TNF- and caspase-8-mediated apoptosis in vivo." (PMID 38734851, 2024). "We demonstrated an unexpected role of caspase-8 auto-cleavage cooperating with RIPK3 or MLKL and RIPK1 in lymphopenia regulation." (PMID 35064213, 2022). "Mice lacking Casp8 in T cells develop RIPK1-driven lymphoproliferative syndromes, whereas we demonstrate that the absence of Ripk1 induces caspase-8-driven lymphopenia and intestinal malignancies." (PMID 40307618, 2025). "Unlike Casp8−/−Ripk3−/− and Casp8−/−Mlkl−/− mice, which resemble the human ALPS and impair cytokine response, we found that Casp8ΔE385/ΔE385Ripk3−/− and Casp8ΔE385/ΔE385Mlkl−/− mice develop hematopoietic cell-intrinsic lymphopenia and myeloid bias." (PMID 35064213, 2022).
metastatic tumors (5 papers, 2010 to 2025). "Mechanistically, caspase 8 loss within the pre-tumoral niche promotes inflammation marked by increased recruitment of regulatory T cells (Tregs) which are responsible for the promotion of metastatic disease." (PMID 41413044, 2025). "In summary, our IHC analysis of caspase-8 and DR5 in HNSCC suggest that a loss or downregulation of DR5 expression and possibly caspase-8 expression may be associated with more metastatic tumors and a loss of differentiation." (PMID 20808443, 2010). "Patient 5 had somatic mutations in HRAS p.G13C, CASP8 p.R127* and PDGFRA p.R764H at all sub-sites in primary and metastatic tumor samples again consistent with these being truncal events." (PMID 27034009, 2016). "Taken together, these results provide evidence that lack of caspase 8 expression is an inherent feature of the majority of human SCLC and recapitulation of this feature in a genetically engineered mouse model reveals that it serves progression to metastatic disease." (PMID 41413044, 2025).
multiple sclerosis (5 papers, 2018 to 2025). A progressive autoimmune disorder affecting the central nervous system resulting in demyelination. "Caspase-8 inhibition has been implicated in multiple sclerosis where cortical lesions showed reduced caspase-8 activity and an increase in cFLIP, (an inhibitor of caspase-8)." (PMID 41440004, 2025). "Caspase-8 activation in microglia has been reported previously in vitro in response to challenge with LPS and other inflammatory stimuli, as well as in microglia in brain tissue from patients with multiple sclerosis (MS)." (PMID 34758843, 2021). "Recently it was shown that in certain pathological conditions, such as multiple sclerosis, microglia present defective caspase-8 activation, which may promote inflammation through activation of necroptosis, thus contributing to disease progression." (PMID 30062059, 2018). "Caspase-8 activation has been reported to be the key event to determine apoptotic fate of cells, and defective activation of caspase-8 is critical for RIP1/RIP3/MLKL signaling to induce oligodendrocyte necroptosis in multiple sclerosis." (PMID 34725188, 2021).
myocardial infarction (5 papers, 2016 to 2023). Gross necrosis of the myocardium, as a result of interruption of the blood supply to the area, as in coronary thrombosis. "Importantly, transplantation of CASP8 shRNA-modified human MSCs (hMSCs) attenuated cardiac fibrosis and improved heart function after myocardial infarction (MI)." (PMID 39872744, 2022). "We have previously hypothesized that the activation of caspase-3 and caspase-8 during the first days of reperfusion can be related to the inflammatory state induced by the release of pro-inflammatory cytokines during myocardial infarction." (PMID 30486235, 2018). "Here, we demonstrated the over-expression of TNF-α, Fas and caspase-8 during myocardial infarction, suggesting that the three aforesaid expressions might play a role in myocardial apoptosis." (PMID 27021411, 2016).
non-alcoholic steatohepatitis (5 papers, 2017 to 2024). "Caspase-8, the apical initiator in death receptor-mediated apoptosis, has been implicated in acute liver injury and in non-alcoholic steatohepatitis." (PMID 29072704, 2017). "CASP8 is a key suppressor of nonalcoholic steatohepatitis (NASH) metabolic disorders and a therapeutic target for T2DM patients." (PMID 37957232, 2023). "Caspase 8 and FADD-like apoptosis regulator (CFLAR) has been identified as a potent factor in mitigating non-alcoholic steatohepatitis (NASH) by inhibiting the N-terminal dimerization of apoptosis signal-regulating kinase 1 (ASK1)." (PMID 39063139, 2024). "Targeting CASP8 and FADD-like apoptosis regulator ameliorates nonalcoholic steatohepatitis in mice and nonhuman primates." (PMID 35846147, 2022).
rheumatoid arthritis (5 papers, 2017 to 2025). A chronic, systemic autoimmune disorder characterized by inflammation in the synovial membranes and articular surfaces. "A genome-wide association study meta-analysis revealed an SNP associated with risk of rheumatoid arthritis (RA) development within the locus containing the gene encoding for caspase-8." (PMID 28978351, 2017).
systemic inflammatory response syndrome (5 papers, 2021 to 2025). SIRS is a serious condition related to systemic inflammation, organ dysfunction, and organ failure. "Although multiple studies have shown that caspase-8 can directly cleave pro-IL-1β into mature IL-1β in circumstances such as TNF-α-induced systemic inflammatory response syndrome (SIRS), mature IL-1β fragments were undetectable in caspase-1-deficient macrophages upon nigericin treatment." (PMID 41208996, 2025). "In a mouse model of systemic inflammatory response syndrome (SIRS), the combined loss of MLKL (or RIPK3) and caspase-8 provides significant protection, suggesting that necroptosis and apoptosis coexist in the inflammation mechanism." (PMID 34594225, 2021). "This is further supported by studies showing that inhibition of necroptosis partially protects mice from systemic inflammatory response syndrome induced by injection of high dose recombinant TNF in the absence of caspase-8 inhibition." (PMID 33858959, 2021). "In addition, silencing of miR-21 protects mice from TNF-α-induced systemic inflammatory response syndrome (SIRS), and this process involves silencing of miR-21 to increase the activity of caspase 8, and then downregulating the expression of RIP1/RIP3 to inhibit the formation of microsomes." (PMID 35509084, 2022). "To demonstrate scalability, we used automated immunohistochemistry to characterize the expression of Caspase-8, RIPK1 and RIPK3 across six tissues during TNF-induced systemic inflammatory response syndrome (SIRS)—a widely-used model of RIPK-dependent pathology." (PMID 38750308, 2024).
ulcerative colitis (5 papers, 2020 to 2023). An inflammatory bowel disease involving the mucosal surface of the large intestine and rectum. "In this study, celastrol markedly up-regulated cleaved caspase-8 level after SAH, which was consistent with previous study in ulcerative colitis." (PMID 34182541, 2021). "In the model mice of ulcerative colitis, the expression of TNF-α was increased; conversely the level of caspase 8 was decreased in the inflamed colonic epithelium (p < 0.05 vs. normal mice)." (PMID 33041798, 2020).
ZIKV infection (5 papers, 2017 to 2025). "Taken together, these results demonstrated that ZIKV infection causes pyroptosis of JEG-3 cells via the TNF-α-caspase-8-caspase-3-GSDME signaling pathway." (PMID 35972780, 2022). "Since caspase 8 is also involved in the regulation of apoptosis, we suggest that elevated levels of caspase 8 due to ZIKV infection may contribute to the cell death via caspase 8 associated mechanisms." (PMID 29167459, 2017). "In summary, our study reveals the critical role of c-FLIP as a positive regulator in caspase-8/3-mediated apoptosis during ZIKV infection, significantly contributing to the development of CZS." (PMID 39038037, 2024). "We ensured a knockdown efficiency of caspase-8 and caspase-3 at least 50% followed by ZIKV infection." (PMID 39038037, 2024). "Our findings demonstrate that c-FLIP promotes ZIKV infection in placental cells and myeloid-derived macrophages, involving inflammation and caspase-8/3-mediated apoptosis." (PMID 39038037, 2024). "In both human trophoblast cells and murine-derived macrophages, we observed that c-FLIP facilitated ZIKV infection by modulating caspase-8/3-mediated apoptosis." (PMID 39038037, 2024). "The deletion of RIG-I significantly inhibited the LDH release and the activation of GSDME, as well as its upstream caspase-3 and caspase-8 during ZIKV infection, while the KO of MDA5 or MAVS only slightly suppressed this process." (PMID 35972780, 2022). "Consistent with our previous observations in JEG-3 cells, the upregulation of RIG-I caused by ZIKV infection was also seen in MTC, and inhibition of either caspase-3 or caspase-8 prominently blocked ZIKV-induced activation of GSDME." (PMID 35972780, 2022). "Here, we report that ZIKV infection activates caspase-3 via the caspase-8-mediated extrinsic apoptotic pathway, which in turn activates GSDME to induce the pyroptosis of placental trophoblasts." (PMID 35972780, 2022). "To delineate the molecular mechanism by which cellular pyroptosis was instigated under ZIKV infection, we detected the activation of caspase-8 and caspase-9 in infected JEG-3 cells by the Western blot analysis." (PMID 35972780, 2022). "As expected, ZIKV infection triggered the activation of both caspase-8 and caspase-9, revealing the fact that various biological processes are triggered during ZIKV infection." (PMID 35972780, 2022). "Notably, ZIKV infection led to a noticeable increase in cleaved caspase-8 (lane 7 vs lane 5) on day 4, and in cleaved caspase-3 (lane 7 vs lane 5) on day 4 post-infection in WT macrophages." (PMID 39038037, 2024). "However, in vitro, our findings indicate that c-FLIP regulates ZIKV infection by activating both caspase-8 and caspase-3 in macrophages and HTR8 cells." (PMID 39038037, 2024). "Therefore, we sought to determine whether ZIKV infection upregulates caspase 8 transcription in monocytes." (PMID 29167459, 2017). "In this study, we uncover that RIG-I, a cytoplasmic dsRNA sensor, can recruit caspase-8, RIPK1, ASC, caspase-1, and NLRP3, forming a more complex PANoptosome to activate PANoptosis following ZIKV infection." (PMID 41263557, 2025). "We further elucidated that ZIKV infection drives PANoptosome formation, with RIG-I nucleating the complex by recruiting ASC, caspase-1, NLRP3, caspase-8, and RIPK1 to activate PANoptosis." (PMID 41263557, 2025). "This indicates reduced caspase-8 and caspase-3 activity with the reduction of c-FLIP expression upon ZIKV infection." (PMID 39038037, 2024). "Overall, these results indicate that both caspase-8 and caspase-3 are involved in the c-FLIP regulating ZIKV infection in macrophage." (PMID 39038037, 2024). "Our findings elucidate that c-FLIP actively promotes ZIKV infection, thereby contributing to CZS through caspase-8/3-mediated apoptosis." (PMID 39038037, 2024). "Given the reported role of c-FLIP as a regulator of apoptosis mediated by caspase-8 and caspase-3, we sought to investigate whether c-FLIP facilitates ZIKV infection through apoptosis." (PMID 39038037, 2024).
ZIKV infection (continued). "Notably, during ZIKV infection, we observed reduced activation of caspase-3, rather than caspase-8, in the c-Flip+/–fetal head compared to the WT fetal head." (PMID 39038037, 2024). "We demonstrated that ZIKV infection could induce placental pyroptosis through the recognition of the viral genome by RIG-I followed by TNF-α release, which activates the caspase-8- and caspase-3-mediated cleavage of pyroptosis executor GSDME in placental cells." (PMID 35972780, 2022). "Based on the quantification, the ratio of cleaved caspase-8 and caspase-3 to total caspase-8 and caspase-3 is significantly lower in the c-FLIP knockdown group compared to the control group upon ZIKV infection while no significant was observed in non-infected group." (PMID 39038037, 2024).
Autoimmunity (4 papers, 2014 to 2025). The occurrence of an immune reaction against the organism's own cells or tissues. "Thus caspase-8 loss in T cells appears to have antagonizing effects on autoimmunity associated with Bim deficiency, suggesting a role for necroptosis in the suppression of autoimmunity." (PMID 24587805, 2014). "Overexpression of catalytically inactive AtMC1 in a Wt background does not lead to autoimmunity in a similar way as Wt CASP8 alleles can suppress the inactive CASP8-dependent inflammatory phenotypes in mice." (PMID 40113992, 2025). "Strikingly, we observed remarkable similarities in the phenotypes derived from expression of catalytically inactive caspase 8 (CASP8 CA) in mammals and overexpression of catalytically inactive AtMC1 in plants, both leading to some form of autoimmunity." (PMID 40113992, 2025). "We also showed that overexpression of non-cleavable AtMC1 variants that carry point mutations either at the putative prodomain cleavage site (R49) or at the Ca2+ binding site does not result in severe autoimmunity in a similar manner as non-cleavable mice CASP8 does not lead to inflammation." (PMID 40113992, 2025).
brain infarction (4 papers, 2015 to 2024). Tissue necrosis in any area of the brain, including the cerebral hemispheres, the cerebellum, and the brain stem. "Pyroptosis-related genes Casp8, Gsdmd and Trem2 were screened out in cerebral infarction by bioinformatics, and they were verified to be highly expressed in cerebral infarction." (PMID 38348100, 2024). "Taken together, pyroptosis-related genes Casp8, Gsdmd, and Trem2 exhibited higher expression levels in the brain tissues of mice with cerebral infarction." (PMID 38348100, 2024). "This study highlighted the regulatory role of Casp8, Gsdmd and Trem2 in pyroptosis, underscoring their potential impact on cerebral infarction." (PMID 38348100, 2024). "For example, muskone can inhibit the expression of Fas and caspase-8 in the cortex, thereby inhibiting apoptosis of neural cells and significantly reducing the volume of cerebral infarction." (PMID 32714405, 2020). "Casp8, Gsdmd and Trem2 can regulate pyroptosis, thus affecting cerebral infarction." (PMID 38348100, 2024). "In addition, the high expression of Casp8, Gsdmd and Trem2 in mice with cerebral infarction was confirmed by animal experiments." (PMID 38348100, 2024). "In addition, we constructed a mouse MCAO model through animal experiments, and confirmed the high expression of pyroptosis-related genes Casp8, Gsdmd and Trem2 in the brain tissues of mice with cerebral infarction." (PMID 38348100, 2024). "Therefore, Casp8 can be a potential therapeutic target for patients with cerebral infarction." (PMID 38348100, 2024). "TGR5 activation by INT777 significantly decreased pro-inflammatory cytokine, cleaved caspase-8, and NLRP3 levels, thereby reducing brain infarctions; both short- and long-term neurobehavioral assessments showed improvements." (PMID 33531049, 2021).